PTPN2 (protein tyrosine phosphatase non-receptor type 2)
Diseases named in the same sentence as PTPN2 in open-access papers (continued):
Sharing a sentence is not in itself a finding about the gene and the disease.
Autoimmunity (27 papers, 2011 to 2025). The occurrence of an immune reaction against the organism's own cells or tissues. "The PTPN2 gene, which encodes TC-PTP, appears to be crucial in regulating immune responses, and certain polymorphisms in this gene can elevate the risk for autoimmunity." (PMID 39944077, 2025). "Ptpn2-deficient mice display systemic inflammation and autoimmunity whilst reduced Ptpn2 expression can exacerbate autoimmunity." (PMID 39241920, 2024). "Loss-of-function variants of TC-PTP-encoding PTPN2 are major genetic determinants of autoimmunity in humans, and deletion of TC-PTP in T cells causes spontaneous autoimmunity." (PMID 36328244, 2022). "Consistent with the key role of PTPN2 loss of function in autoimmunity, recent studies have also validated PTPN2 as an important target for cancer immunotherapy." (PMID 33055428, 2020). "The inflammation and spontaneous autoimmunity caused by PTPN2 deficiency in T cells can therefore be attributed to self-antigen-mediated increases in TCR sensitivity and the enhanced responses to common γ-chain cytokines." (PMID 32726622, 2020). "Our model contributes to clarifying how genetic risk factors for autoimmunity interact with the gut microenvironment in the pathogenesis of disease and is particularly fitting for genes, such as PTPN2, that are shared between IBD and RA or SpA." (PMID 33055428, 2020). "Older T-cell-specific TC-PTP-deficient (Ptpn2−/−) mice suffer from spontaneous autoimmunity corresponding with enhanced activation of both CD4 and CD8 T cells in vivo, leading to a reduction in the T-cell receptor (TCR) threshold of activation." (PMID 30208623, 2018). "In mice, PTPN2 deficiency results in perturbations of T cell tolerance and enhanced T cell and B cell responses, resulting in severe inflammatory disease and autoimmunity." (PMID 29755505, 2018). "Single nucleotide polymorphisms in the gene encoding the protein tyrosine phosphatase TCPTP (encoded by PTPN2) have been linked with the development of autoimmunity." (PMID 22590589, 2012). "Whereas the originally reported association between PTPN2 and autoimmunity was to rs2542151, the SNPs which were tested and found associated with GD (i.e. rs1893217 and rs478582) were those which showed stronger association to T1DM than rs2542151." (PMID 22654555, 2011). "The aim of our study was to investigate whether the autoimmunity risk gene, PTPN2, which also confers elevated risk to develop inflammatory bowel disease, affects susceptibility to SARS-CoV-2 viral uptake." (PMID 39756517, 2025). "PTPN2 deficiency in T cells can result in inflammation/autoimmunity in aged C57BL/6 mice." (PMID 31803974, 2020). "Moreover, loss of Ptpn2 resulted in severe systemic inflammation and autoimmunity and increased number of immune cells in mice." (PMID 29764444, 2018). "PTPN2 is highly expressed in hematopoietic cells and the phenotype of the knockout mouse model indicates its important role in immune system development, function and predisposition to autoimmunity." (PMID 22654555, 2011). "Moreover, it has been documented that PTPN2 single nucleotide polymorphisms (SNPs) are linked to dysfunctional protein products with subsequent increment of proinflammatory cytokines production, upregulation of Th2 and Th17, downregulation of TReg, and the development of autoimmunity." (PMID 39320556, 2024). "Accordingly, we assessed the impact of systemically targeting PTP1B and PTPN2 with Compound 182 in tumor-bearing mice on the development of systemic inflammation and autoimmunity." (PMID 37500611, 2023). "Yet as a broader understanding of the impact of altered PTPN2 expression is gained, its role in autoimmunity has extended beyond T cells." (PMID 35979360, 2022). "In fact, deletion of PTPN2 in mature T cells results in autoimmunity in aged mice, possibly due to a decreased threshold for T-cell receptor (TCR) signaling." (PMID 29789628, 2018).
Autoimmunity (continued). "Genome wide association studies (GWAS) and recent identification of loss-of-function gene variants in individuals with young-onset autoimmunity have highlighted a role for protein tyrosine phosphatase nonreceptor type 2 (PTPN2) in development of autoimmunity." (PMID 41424386, 2025). "In T cells, PTPN2 is a negative regulator of both T cell receptor (TCR) signalling and JAK-STAT pathways, whilst PTPN2 polymorphisms have been identified as risk factors for the development of autoimmunity." (PMID 38334623, 2024). "To further explore any impact of PTPN2 deficiency on the development of inflammatory disease, we increased the number of adoptively transferred CAR T cells from 6 × 106 to 20 × 106 and monitored for inflammation and autoimmunity." (PMID 31803974, 2020). "TC-PTP (PTPN2) is a negative regulator of LCK and conditional Ptpn2 knock-out in mouse peripheral T cells results in inflammation and autoimmunity." (PMID 31297117, 2019). "The phosphatase Ptpn2 was also an enriched hit, consistent with its established negative regulatory role in CD8+ T cells in autoimmunity and tolerance." (PMID 30971695, 2019). "Since PTP1B and PTPN2 can function as intracellular checkpoints to tune T cell responses, one possible adverse consequence of systemically targeting PTP1B and PTPN2 with small molecule inhibitors may be the development of CRS and autoimmunity." (PMID 37500611, 2023). "A T cell-specific deletion of PTPN2 promotes the development of systemic inflammation and autoimmunity in otherwise non-autoimmune-prone C57BL/6 mice and accelerates the onset of type 1 diabetes in autoimmune-prone non-obese diabetic (NOD) mice." (PMID 32726622, 2020). "Most importantly, this was achieved in the absence of the development of cytokine release syndrome or autoimmunity, suggesting that targeting PTPN1 and PTPN2 in vivo may not be associated with overt immune-related toxicities." (PMID 37766318, 2023). "Taken together our findings demonstrate that systemic targeting of PTP1B and PTPN2 with a small molecule inhibitor can effectively repress tumor growth without necessarily promoting CRS and autoimmunity." (PMID 37500611, 2023).
colitis (25 papers, 2010 to 2026). Inflammation of the colon. "Macrophage-specific Ptpn2 deletion is known to protect against colitis-associated tumor formation in mice in an inflammasome and IL1β-dependent manner." (PMID 36968224, 2023). "The anti-inflammatory role of PTPN2 is highlighted by the fact that PTPN2-deficient mice die a few weeks after birth because of systemic inflammation and severe colitis." (PMID 36077422, 2022). "Given the profound changes in T cell subsets in the lamina propria of PTPN2fl/flxCD11cCre mice, we further characterized the effect of PTPN2-deficiency in DCs in a T cell-driven colitis model." (PMID 34201918, 2021). "To address this knowledge gap, we investigated the relationship between the food additive TiO2 and genetically caused Ptpn2 dysfunction in myeloid cells during the course of DSS-induced colitis in vivo." (PMID 33466682, 2021). "In contrast, loss of PTPN2 in myeloid cells promotes intestinal inflammation while protecting from colitis-associated tumor formation via increased inflammasome assembly and subsequent IL-1β production/maturation." (PMID 34201918, 2021). "This indicates that macrophages indeed seem to counteract the proinflammatory nature of PTPN2-deficient DCs in the inflamed intestine and that their loss results in elevated colitis severity in PTPN2fl/flxCD11cCre mice." (PMID 34201918, 2021). "The loss of expression of the IBD risk gene Ptpn2 in myeloid cells resulted in a different profile in the severity of colitis in mice exposed to TiO2." (PMID 33466682, 2021). "In the T cell transfer colitis model, the introduction of PTPN2 deficient CD4+ T cells resulted in an almost 3-fold increase in the frequency of IFNγ producers and a 2-fold increase in the frequency of IFNγ+ IL17+ double producers." (PMID 30429852, 2018). "However, macrophage depletion by clodronate caused enhanced colitis severity in mice with a DC-specific loss of PTPN2." (PMID 34201918, 2021). "Given the increased infiltration of innate and adaptive immune cells into the lamina propria of PTPN2fl/flxCD11cCre mice, we next set out to investigate how the loss of PTPN2 in DCs might affect inflammation during colitis induction." (PMID 34201918, 2021). "Thus, the loss of PTPN2 in macrophages causes more severe colitis, which may be mitigated by inhibiting IL-1β." (PMID 36077422, 2022). "Moreover, inhibition of IL-1β rescued mice from increased colitis in PTPN2-deficient mice." (PMID 33808793, 2021). "The key role of PTPN2 in regulating immune reactions during intestinal inflammation has been described for innate and adaptive immune cells using mice deficient for PTPN2 in macrophages or T cells, which resulted in an elevated susceptibility to experimental colitis." (PMID 34201918, 2021). "The aim of the present study was to determine whether the alterations in intestinal microbiota composition observed in mouse colitis models in T-cell specific PTPN2 deficient mice are comparable to the alterations in intestinal microbiota composition observed in IBD patients." (PMID 29965986, 2018). "Deficiency of protein tyrosine phosphatase non-receptor type 2 (PTPN2) causes early death in mice due to systemic inflammation and severe colitis." (PMID 33808793, 2021). "Using mice with a specific loss of Ptpn2 in myeloid cells, we were able to demonstrate that TiO2 treatment shows different profiles in the extent of DSS-induced experimental colitis in Ptpn2LysMCre and Ptpn2fl/fl mice." (PMID 33466682, 2021). "Together, PTPN2 plays an inhibitory role in the development of colitis by regulating inflammasome activation and IL-1β production." (PMID 33808793, 2021). "In IBD, MAGI2, GNAI2, MIO9B, PTPN2, and CDH1 genes have been identified as tight junction assembly and barrier function regulators and were significantly associated with colitis." (PMID 33806347, 2021).
colitis (continued). "Since PTPN2fl/flxCD11cCre mice showed elevated levels of macrophages, and these macrophages express elevated levels of PTPN2, we hypothesized that macrophages might compensate for the loss of PTPN2 in dendritic cells in our mice and counteract their proinflammatory action upon colitis induction." (PMID 34201918, 2021). "The aim of this study was to investigate the DC-specific role of PTPN2 in the intestine during colitis development." (PMID 34201918, 2021). "Lack of Ptpn2 expression in either T cells or myeloid cells resulted in a more severe colitis and knockdown of PTPN2 in intestinal epithelial cells induced the expression of pro-inflammatory mediators." (PMID 33466682, 2021). "To model such interaction, we assessed the effect of PTPN2 haploinsufficiency in a potentially new model of arthritis induced by subclinical colonic inflammation in SKG mice." (PMID 33055428, 2020). "Inducible Treg-specific haploinsufficiency of Ptpn2 enhanced colitis-induced SKG arthritis and led to specific joint accumulation of GPR15+ exTregs." (PMID 33055428, 2020). "Treg-specific Ptpn2 haploinsufficiency enhances SKG arthritis induced by subclinical colonic inflammation." (PMID 33055428, 2020). "A recent study identified the dual role for PTPN2 in directly regulating inflammasome activation and IL‐1β production to suppress pro‐inflammatory responses during colitis but promote intestinal tumor development." (PMID 32207560, 2020). "In the T cell transfer colitis model, the transfer of naïve PTPN2−/− CD4+ T cells resulted in an earlier onset of disease, as well as an increased in weight loss, spleen weight and macroscopic signs of colitis." (PMID 30429852, 2018). "The loss of PTPN2 has been shown to alter CD4+ T cell differentiation, impacting disease severity in multiple murine colitis models." (PMID 30429852, 2018). "Despite this striking phenotype in homozygous PTPN2-deficient mice, PTPN2-heterozygous (Het) mice do not show signs of spontaneous systemic inflammation, although PTPN2 expression is reduced and these mice have been reported to exhibit a more severe response to chemical colitis models." (PMID 36810248, 2023). "During induced intestinal inflammation, the loss of PTPN2 in DCs has no appreciable impact on colitis severity since those macrophages are able to compensate for the proinflammatory effect of PTPN2-deficient DCs." (PMID 34201918, 2021). "In intestinal epithelial cells, loss of PTPN2 promotes inflammatory cytokine secretion and compromises barrier function in vitro but has no overt effect on intestinal inflammation in vivo during experimental DSS-induced colitis." (PMID 34201918, 2021). "However, we demonstrated that the loss of the IBD risk gene Ptpn2 in myeloid cells produces a different pattern and a most robust tendency in the effects of TiO2 in the DSS acute model of experimental colitis." (PMID 33466682, 2021). "Colitis induction led to a shortening of the colon in DSS-treated animals but DC-specific PTPN2-deficiency had no impact." (PMID 34201918, 2021). "DC-specific PTPN2 deletion promoted infiltration of B and T lymphocytes, macrophages, and DCs into the lamina propria of unchallenged mice and elevated Th1 abundance during acute DSS colitis, suggesting an important role for PTPN2 in DCs in maintaining intestinal immune cell homeostasis." (PMID 34201918, 2021). "Together, these findings demonstrate that PTPN2-deficiency in DCs does not affect colitis severity in a T cell-driven model of intestinal inflammation." (PMID 34201918, 2021). "Furthermore, T cell–specific deletion of PTPN2 results in development of aggressive colitis and signs of systemic autoimmunity." (PMID 33055428, 2020). "This dose of DSS did not cause development of clinical colitis in mice of either genotype but resulted in more significant inflammatory infiltration in colons of Ptpn2+/– mice when compared with WT mice." (PMID 33055428, 2020).
colitis (continued). "Moreover, although PTPN2‐deficient CAR T cells were increased in the lamina propria (Fig EV4F), there were no signs of overt tissue damage (as assessed histologically) or colitis, as assessed by measuring colon length (Fig EV4G and H)." (PMID 31803974, 2020). "Since PTPN2 has an inhibitory effect on several proinflammatory signaling cascades and plays a role in T cell development, we investigated whether loss of PTPN2 in DCs results in a change in T cell-associated cytokines and transcription factors during DSS-induced colitis." (PMID 34201918, 2021). "However, this did not result in an elevated colitis phenotype, likely because increased infiltration of macrophages in the intestine upon loss of PTPN2 loss in DCs can compensate for the inflammatory effect of PTPN2-deficient DCs." (PMID 34201918, 2021). "However, despite an increased Th1 response upon DC-specific loss of PTPN2, we did not observe any differences in terms of colitis severity in our mouse models." (PMID 34201918, 2021). "Our experiments with macrophage depletion show that the increase of PTPN2-expressing macrophages in the lamina propria upon loss of PTPN2 in DCs can explain why we did not observe spontaneous inflammation or differences regarding the severity of intestinal inflammation upon colitis induction." (PMID 34201918, 2021). "Taken together, this indicates that—in contrast to our hypothesis—loss of PTPN2 in DCs clearly does not promote susceptibility to chronic DSS-induced colitis." (PMID 34201918, 2021). "Taken together, despite the well-described action of PTPN2 on multiple signaling cascades, loss of DC-specific PTPN2 resulted in increased levels of STAT1 phosphorylation in acute DSS-induced colitis but had no drastic changes in the overall inflammatory response." (PMID 34201918, 2021). "Overall, our data show that presence of the IBD-associated variations within the PTPN2 and PTPN22 gene loci are related to significant alterations in intestinal microbiota composition what clearly resembles our previous findings in mouse colitis models using PTPN2 deficient mice." (PMID 29965986, 2018). "Furthermore, spermidine treatment significantly reduces disease severity in mice with DSS-induced colitis; hence, spermidine supplementation and subsequent PTPN2 activation may be helpful in the treatment of chronic intestinal inflammation such as IBD." (PMID 24040033, 2013). "It is well possible that upon erosion of the epithelial barrier following DSS exposure or upon colitis induction via transfer of CD4+ naïve T cells, PTPN2-expressing macrophages are able to take up antigens and trigger subsequent anti-inflammatory immune reactions in PTPN2fl/flxCD11cCre mice." (PMID 34201918, 2021). "Together, these data indicate that PTPN2 in DCs does not affect acute DSS-induced colonic inflammation." (PMID 34201918, 2021). "Together, this indicates that under inflammatory conditions, lack of PTPN2 in DCs promotes the expression of co-stimulatory molecules and affects Th-cell composition; however, this does not appear to provoke elevated colitis severity." (PMID 34201918, 2021). "Although other tissues such as the gut epithelium also express CXCR3 chemokines, and comparatively small increases in PTPN2‐deficient CAR T cells were detected in the colon (lamina propria), this was not accompanied by overt tissue damage or colitis." (PMID 31803974, 2020). "Consistent with the inflammatory phenotype, Ptpn2−/− (BALB/c-129SJ) mice are more susceptible to endotoxic shock and macrophages are hypersensitive to lipopolysaccharide and IFNγ, whereas Ptpn2+/− (BALB/c-129SJ) mice are hypersensitive to dextran sulphate sodium (DSS) and the development of colitis." (PMID 22590589, 2012). "One patient with colonic inflammation, coeliac-like duodenitis, and NLH, who was infected with norovirus and had recurrent episodes of Campylobacter infections, was found to have a loss-of-function mutation in PTPN2 (# 8)." (PMID 34599484, 2022).
Obesity (24 papers, 2012 to 2024). Accumulation of substantial excess body fat. "Overall, the persistence of pSTAT3 in the anti-mesometrial area of HFD mice uteri suggests a potential role for SOCS3 and PTPN2 in mediating obesity-induced changes in decidual function." (PMID 39090270, 2024). "For example, PTPN2 deletion in the liver can facilitate the STAT‐3‐dependent development of hepatocellular carcinoma in obesity." (PMID 31803974, 2020). "From the GWAS, the significant markers associated with obesity-related traits including body weight (CACNA1B, C22orf39, U6, MYH14, PTPN2, SEH1L) and blood sugar (PRSS55, GRIK2), were identified." (PMID 33182249, 2020). "Nevertheless, some of these SNPs (rs1260326 (GCKR), rs13233571 (BCL7B), rs2847281 (PTPN2), and rs4129267 (IL6R) predicting hsCRP and rs630014 (ABO), rs651007 (ABO), and rs687289 (ABO) predicting IL-6) were associated with obesity-related traits." (PMID 28819125, 2017).